PRKCA (protein kinase C alpha)
Diseases named in the same sentence as PRKCA in open-access papers (continued):
Sharing a sentence is not in itself a finding about the gene and the disease.
multiple sclerosis (8 papers, 2006 to 2025). A progressive autoimmune disorder affecting the central nervous system resulting in demyelination. "An observation showed that PRKCA mRNA levels in blood of multiple sclerosis patients were significantly lower, which has been consistent with the results of their experiments that higher levels of PRKCA expression conferred by alleles were related to the protective signal." (PMID 35071383, 2021). "In a more specific example, the multiple sclerosis-associated PRKCA gene is seemingly affected by an intronic sQTL that increases the expression of a gene isoform more prone to nonsense-mediated decay, thereby reducing the likely protective PRKCA mRNA levels post-transcriptionally." (PMID 31937202, 2020). "PRKCA is involved in immune cell trafficking, and ITGB3 is coding for integrin β3 expression, which is associated with autoimmune conditions including multiple sclerosis." (PMID 40262193, 2025). "Analogously, in peripheral blood monocytes (PBMCs) of patients with multiple sclerosis (MS), hsa_circ_0001742 competitively binds to miR-634, which is transcribed from PRKCA gene introns, thus regulating the PRKCA expression." (PMID 33717126, 2021).
acute myeloid leukemia (7 papers, 2014 to 2025). Acute myeloid leukemia (AML) is a group of neoplasms arising from precursor cells committed to the myeloid cell-line differentiation. "For instance, a multi-kinase inhibitor midostaurin (PRKCA as one of the targets) has been approved for acute myeloid leukemia therapy." (PMID 32802198, 2020).
breast tumors (7 papers, 2003 to 2023). "It has been reported that the expression of PRKCA is associated with endocrine resistance and poor prognosis in ER-positive (ER +) breast tumors." (PMID 38081857, 2023).
Cognitive impairment (7 papers, 2012 to 2023). Abnormal cognition is characterized by deficits in thinking, reasoning, or remembering. "In this study, the PRS of PRKCA was strongly associated with cognitive impairment, which was favorably consistent with previous studies and animal experiments." (PMID 37107586, 2023). "A link between possession of the PRKCA homozygous A variant and reduced episodic recall has been previously identified in people with schizophrenia who exhibit cognitive impairment." (PMID 24842701, 2014). "In summary, this case–control study based on northern Chinese older people verified associations between the calcium signaling pathway gene and cognitive function and identified an interaction effect between PRKCA gene variants and bone mineral density on mild cognitive impairment." (PMID 37107586, 2023).
liver cancer (7 papers, 2015 to 2024). An epithelial or non-epithelial malignant neoplasm that arises from the liver. "Specifically, four HRGs, decorin (DCN), DNA damage inducible transcript 4 (DDIT4), protein kinase C alpha (PRKCA), and N-myc downstream regulates gene-1 (NDRG1), were included in the hypoxic risk model for liver cancer that the researchers created." (PMID 38911968, 2024).
atherosclerosis (6 papers, 2015 to 2025). A disease characterized by the build-up of fatty material and calcium deposition in the arterial wall resulting in partial or complete occlusion of the arterial lumen. "The targets of ATK2, IKBKB, RAF1, CHUK, TNF, JUN, and PRKCA were mainly involved in fluid shear stress and the atherosclerosis and PI3K-Akt signaling pathways." (PMID 29177114, 2017). "ATK2, IKBKB, RAF1, CHUK, TNF, JUN, and PRKCA were mainly involved in fluid shear stress and the atherosclerosis pathways, pathways in cancer, and the PI3K-Akt signaling pathway." (PMID 29177114, 2017).
chondrosarcoma (6 papers, 2010 to 2025). A malignant cartilaginous matrix-producing mesenchymal neoplasm arising from the bone and soft tissue. "The early onset chondrosarcomas associated with the heterozygous knock-in of the penetrant chordoid glioma-associated PRKCA D463H mutation in mice and the lack of any phenotype associated with the related D463N mutant knock-in suggests that this mutation confers an in vivo gain-of-function." (PMID 41187221, 2025).
cryptosporidiosis (6 papers, 2020 to 2024). Intestinal infection with organisms of the genus Cryptosporidium. "Single nucleotide polymorphisms (SNPs) in the human protein kinase C-α (PRKCA) gene region have been associated with susceptibility to cryptosporidiosis." (PMID 35099276, 2022). "Six SNPs in an intron of PRKCA (protein kinase C alpha) were associated with increased risk for symptomatic Cryptosporidium infections during the first year of life." (PMID 35646724, 2022). "Recently, we found that variation within the PRKCA gene was associated with increased susceptibility to cryptosporidiosis in children." (PMID 35099276, 2022). "More recently an intronic SNP (rs58296998) in the protein kinase C gene (PRKCA) identified by a genome-wide association study was found to be associated with higher risk of cryptosporidiosis in the first year of life among 873 children in Bangladesh." (PMID 34583337, 2021). "We identified a genetic variant within protein kinase C alpha (PRKCA) associated with higher risk of cryptosporidiosis in the first year of life." (PMID 32019797, 2020). "This genetic association suggests a role for protein kinase C alpha in pediatric cryptosporidiosis and warrants further investigation." (PMID 32019797, 2020). "These expression data, coupled with the GWAS result, suggested that decreased expression of PRKCA is correlated with increased risk of symptomatic Cryptosporidium infection within the first year of life." (PMID 32019797, 2020). "Identifying host genetic variations associated with cryptosporidiosis, such as those in PRKCA, can help us identify viable drug targets to improve treatment and prevention of this major cause of morbidity and mortality." (PMID 32019797, 2020). "Through a GWAS meta-analysis of three separate birth cohorts, we identified a region in PRKCA on chromosome 17 as being associated with increased risk of symptomatic cryptosporidiosis in the first year of life among Bangladeshi infants." (PMID 32019797, 2020). "A region on chromosome 17 was identified, with each additional T allele of rs58296998, an intronic SNP in PRKCA, conferring 2.4 times the odds of cryptosporidiosis within the first year of life." (PMID 32019797, 2020). "We identified a SNP that was associated with decreased expression of PRKCA and thus was less able to mediate the IL-17 immune response during Cryptosporidium infection." (PMID 32019797, 2020). "A total of 6 SNPs in an intron of PRKCA (protein kinase c, alpha) were significantly associated with Cryptosporidium infection (P < 5 × 10−8)." (PMID 32019797, 2020). "Our studies therefore provide insight into how polymorphisms in human PRKCA may increase susceptibility to cryptosporidiosis in children, suggesting that increased PKCα activity may increase permissibility to infection at the intestinal epithelium." (PMID 35099276, 2022). "For cryptosporidiosis, candidate gene studies indicating an increased risk of cryptosporidiosis include HLA class I and II genes, SNPs in the mannose binding lectin (MBL) gene, and variation within the protein kinase C alpha (PRKCA) gene." (PMID 33195574, 2020). "This suggests that this SNP may influence Cryptosporidium infection through decreased expression of PRKCA." (PMID 32019797, 2020). "Our findings suggest that SNPs associated with increased susceptibility to Cryptosporidium might act via increased PKCα activity during Cryptosporidium infection, either by increasing PRKCA mRNA expression or via compensatory gene regulation of PKCα regulators." (PMID 35099276, 2022).
Hypertension (6 papers, 2008 to 2024). The presence of chronic increased pressure in the systemic arterial system. "The results indicate that in the Ang II-induced hypertension group, the expression levels of TNF, NFKB1, MAPK3, PTGS2, and RELA were markedly elevated compared to the control group, while the expression levels of HSP90AA1, HSP90AB1, PPARG, SIRT1, MAPK1, and PRKCA were significantly decreased." (PMID 39592923, 2024).
Anxiety (5 papers, 2018 to 2024). Intense feelings of nervousness, tension, or panic often arise in response to interpersonal stresses. "Several anxiety-associated genes had direct interactions with striatal development genes, such as PRKCA with ADCY5 and DLX3, and ESR1 with ISL1." (PMID 34526518, 2021). "Moreover, nonioside E was docked with PRKCA to explore the impact of the unique compound on anxiety." (PMID 39337965, 2024).
intestinal tumors (5 papers, 2017 to 2023). "Consistent with this hypothesis, PRKCA knock-out has been associated with higher tendency to develop spontaneous intestinal tumors in wild type mice, and with more aggressive tumors and reduced survival rate in APCmin/+ mice." (PMID 31109112, 2019).
malignant glioma (5 papers, 1999 to 2025). A grade III or grade IV glioma arising from the central nervous system. "Trametinib effectively blocked the colony formation of immortalized human astrocytes expressing D463H mutant PRKCA, while causing only a mild reduction in colony formation for the malignant glioma cell lines with wild-type PRKCA alleles." (PMID 29476136, 2018).
papillary glioneuronal tumor (5 papers, 2015 to 2022). A WHO grade I, indolent and relatively circumscribed brain tumor. "SLC44A1 (solute carrier family 44)-PRKCA (PKCα) fusion oncogene was detected in papillary glioneuronal tumor with the rearrangement of chromosomes 9 and 17, thus leading to constitutive PKCα activation." (PMID 35267413, 2022). "No PRKCA fusions or kinase domain mutations were identified in any of the cases, suggesting that gangliogliomas are genetically distinct from the majority of papillary glioneuronal tumors and chordoid gliomas." (PMID 29880043, 2018).
schizophrenia (5 papers, 2014 to 2024). A major psychotic disorder characterized by abnormalities in the perception or expression of reality. "Protein kinase Cα (PKCα/PRKCA) is a crucial regulator of circadian rhythm and is associated with human mental illnesses such as autism spectrum disorders and schizophrenia." (PMID 36835261, 2023). "Consistent with the importance of PRKCA in regulating the circadian rhythm and the strong association between circadian rhythm disruption and mental health, the mutation of Prkca is strongly associated with human mental illnesses such as autism spectrum disorders (ASD) and schizophrenia." (PMID 36835261, 2023).
intervertebral disc degeneration (4 papers, 2023 to 2025). "For example, tsRNA-04002 alleviates intervertebral disc degeneration by targeting PRKCA to inhibit apoptosis of nucleus pulposus cells." (PMID 39870617, 2025). "Conversely, tsRNA-04002 inhibits apoptosis in nucleus pulposus cells by targeting PRKCA, thereby alleviating intervertebral disc degeneration." (PMID 40809958, 2025). "For instance, tsRNA-3043a promotes apoptosis in ovarian granulosa cells by targeting FLT1, thereby exacerbating premature ovarian insufficiency, In contrast, tsRNA-04002 inhibits apoptosis in nucleus pulposus cells by suppressing PRKCA, thus delaying intervertebral disc degeneration." (PMID 40809958, 2025). "tsRNA-04002 alleviates Intervertebral disk degeneration (IDD) by targeting PRKCA." (PMID 38596214, 2024).
Barrett esophagus (3 papers, 2017 to 2022). Esophageal lesion lined with columnar metaplastic epithelium which is flat or villiform. "The second critical gene is PRKCA that is also involved in BE, esophagitis, esophageal squamous cell carcinoma, and adenocarcinoma of esophagus." (PMID 30774811, 2018). "We found that the expression levels of both PLCE1 and PRKCA were significantly elevated in human esophagitis, esophageal squamous cell carcinoma, Barrett's esophagus, esophageal adenocarcinoma and in NMBA-treated rat esophageal epithelia." (PMID 28402280, 2017). "Interestingly, PRKCA was also altered with the changes of PLCE1, suggesting the important significance of their correlation in the development of esophagitis and Barrett's esophagus and their malignant transformation." (PMID 28402280, 2017). "To investigate the changes of PLCE1 and PRKCA in BE and EAC, we deeply mined the Kim's Oncomine data and found that both PLCE1 and PRKCA mRNA levels were dramatically increased in Barrett's Esophagus and EAC, in comparison with the non-tumor esophageal mucosa." (PMID 28402280, 2017).
depression (3 papers, 2019 to 2021). "The second module control downstream FOS to treat depression by targeting the DRD1/DRD5--GNAQ--PLCB1--DAG--PRKCA cascade reaction." (PMID 34867413, 2021). "The PRKCA gene is higher expressed in bipolar mania compared to unipolar depression, and is lower expressed in fibroblasts of patients with BIP treated with lithium compared to those treated with other medications." (PMID 30930738, 2019).
E. coli infection (3 papers, 2013 to 2020). "PRKC (including PRKCA and PRKCB), along with VAV (VAV2 and VAV3) genes also feature in various high ranking immunological pathways including T cell signaling, Pathogenic Escherichia Coli Infection and Natural Killer Cell Mediated Cytotoxicity." (PMID 24278029, 2013).
epilepsy (3 papers, 2014 to 2023). A brain disorder characterized by episodes of abnormally increased neuronal discharge resulting in transient episodes of sensory or motor neurological dysfunction, or psychic dysfunction. "Secondly, the response to lipopolysaccharide is compared to our previous results, where we found reduced expression of PRKCA in epilepsy and stress cardiomyopathy." (PMID 36776884, 2023).
esophageal cancer (3 papers, 2017 to 2021). A primary or metastatic malignant neoplasm involving the esophagus. "Finally, high expression of both PLCE1 and PRKCA is significantly associated with poor outcomes of the patients with esophageal cancers." (PMID 28402280, 2017). "This study analyzed the expression levels of and correlation between PLCE1 and PRKCA in human esophagitis, carcinogen NMBA-induced rat esophagus, PLCE1 genetic deficient mouse esophageal epithelial tissues and human esophageal cancer cell line, integrated with Online oncology data sets." (PMID 28402280, 2017). "With the advances in the management of gastrointestinal cancers, the combination of PLCE1 and PRKCA could be an immune checkpoint for esophageal cancer therapy." (PMID 28402280, 2017). "However, PRKCA and cytokines were significantly downregulated in PLCE1-deficient mouse esophageal epithelia, and knockdown of PLCE1 in human esophageal cancer cells led to reduction of PRKCA and cytokines." (PMID 28402280, 2017). "This study has also strongly suggested that the co-expression of PLCE1 and PRKCA could be an indicator for predicting of esophageal cancer patient outcomes, and the partnership of PLCE1 and PRKCA could be a therapeutic target instead of a single target for personalized therapy or prevention." (PMID 28402280, 2017).
fibrosis (3 papers, 2016 to 2025). the formation of excess fibrous connective tissue in an organ or tissue in a reparative or reactive process. "In summary, we found synergistic effects on cell growth and fibroblast activation after inhibition of DGKA and PRKCA in fibroblasts from patients developing fibrosis." (PMID 26964756, 2016).
glioneuronal tumors (3 papers, 2015 to 2024). "We present the first report of the spatial and temporal co-occurrence of an intracranial arteriovenous malformation traversing and within a papillary glioneuronal tumour, molecularly defined by the presence of SLC44A1::PRKCA fusion." (PMID 39292231, 2024). "Histologically and immunohistochemically, PGNT is not readily differentiated from other glioneuronal tumours; however, SLC44A1::PRKCA fusion appears to be unique to PGNT and is now regarded as its defining molecular feature." (PMID 39292231, 2024).
osteoarthritis (3 papers, 2013 to 2025). A noninflammatory degenerative joint disease occurring chiefly in older persons, characterized by degeneration of the articular cartilage, hypertrophy of bone at the margins and changes in the synovial membrane. "The PRKCA is related to chronic pain of human osteoarthritis and over-expressed mRNA abundance levels in an osteoarthritis rat model." (PMID 34502281, 2021).
radiation fibrosis (3 papers, 2013 to 2024). "Protein and mRNA expression data indicated increased expression of PRKCA in fibroblasts of patients developing radiation fibrosis." (PMID 26964756, 2016).
thyroid cancer (3 papers, 2015 to 2024). "Protein Kinase C alpha (PKCα) a is here remarked as an important marker of thyroid cancer (TC) progression as its expression levels are related to worse clinical and tumor parameters." (PMID 39596225, 2024). "Here, we show for the first time that protein kinase C alpha (PKCα) is the classical PKC isoform with the highest expression in thyroid cancer (TC) cell lines and in TC cancer patients." (PMID 39596225, 2024).
viral infection (3 papers, 2023 to 2026). "Protein kinase C alpha (PKCα) is a central signaling molecule implicated in various cellular processes, including viral infections." (PMID 41738767, 2026).
African trypanosomiasis (2 papers, 2020 to 2023). "These transcripts belong to three genes: IFIH1, TGFB2 and PRKCA, and are associated with three KEGG pathways all related to infection and infection detection (RIG-I-like receptor signaling pathway, Malaria, and African trypanosomiasis)." (PMID 38161589, 2023). "Meanwhile, hsa-miR-4284 was mainly enriched in pathways like morphine addiction (hsa05032; P value, 2.05E−03; gene, protein kinase C alpha (PRKCA)) and African trypanosomiasis (hsa05143; P value, 4.33E−03; gene, PRKCA)." (PMID 32252801, 2020).
astrocytoma (2 papers, 2022 to 2025). "Patients with astrocytoma grades III and IV with low expression of PGR and PRKCA mRNA showed higher survival than those with high expression." (PMID 36358843, 2022).
autoimmune disease (2 papers, 2006 to 2012). A disorder resulting from loss of function or tissue destruction of an organ or multiple organs, arising from humoral or cellular immune responses of the individual to their own tissue constituents. "Taking into account the critical role of the PRKCA and associated cellular pathways in regulating immune response, it may also be involved in other autoimmune diseases." (PMID 16596167, 2006). "The PRKCA gene is one of the key components in a pathway that regulates immune responses, and is located in a region shown to harbor susceptibility gene(s) for several human autoimmune diseases and animal autoimmune/inflammatory disease models." (PMID 16596167, 2006).
brain tumor (2 papers, 2018). "PRKCA D463H mutation appears to define chordoid glioma of the third ventricle and genetically distinguishes it from all other brain tumor types that have been studied to date." (PMID 29476136, 2018).
cervical cancer (2 papers, 2024 to 2025). A primary or metastatic malignant neoplasm involving the cervix. "The molecular docking analysis of the 306 differential proteins with known cervical cancer–related targets identified intersecting proteins within the PI3K/AKT signaling pathway: PIK3R2, GRB2, MAPK1, FGF2, and PRKCA." (PMID 40733070, 2025).
colon adenocarcinoma (2 papers, 1998 to 2016).
cystic fibrosis (2 papers, 2020 to 2022). Autosomal recessive disorder caused by pathogenic variants in the CFTR gene (cystic fibrosis transmembrane conductance regulator), which encodes a chloride and bicarbonate channel expressed in epithelial cells, and follow the diagnosis criteria. "In terms of inflammation or immune response, the activation of PRKCA is involved in a calcium-mediated process participating in cystic fibrosis." (PMID 34983465, 2022).